RNU6-439P (RNA, U6 small nuclear 439, pseudogene)
Gene: Small nuclear RNA gene on chromosome 2 (49,233,794 to 49,233,899, reverse strand). Ensembl gene ENSG00000206915.
Homologues: Orthologues: chimpanzee U6 (98% identical), pig U6 (87% identical), pig U6 (84% identical), mouse Gm25482 (82% identical), rat U6 (82% identical), mouse Gm24388 (80% identical), guinea pig U6 (78% identical), dog U6 (77% identical), rabbit U6 (75% identical). Paralogues in human: RNU6-166P (92% identical), RNU6-41P (92% identical), RNU6-15P (91% identical), RNU6-1011P (90% identical), RNU6-1060P (90% identical), RNU6-12P (90% identical), RNU6-13P (90% identical), RNU6-25P (90% identical), RNU6-26P (90% identical), RNU6-31P (90% identical), RNU6-32P (90% identical), RNU6-38P (90% identical), and 1289 more.